DYRK1B (dual specificity tyrosine phosphorylation regulated kinase 1B)
Diseases named in the same sentence as DYRK1B in open-access papers (continued):
Sharing a sentence is not in itself a finding about the gene and the disease.
melanoma (4 papers, 2016 to 2024). A malignant, usually aggressive tumor composed of atypical, neoplastic melanocytes. "The miR-126 inhibits invasion and migration in cervical cancer cells by binding to ZEB1; the miR-126-3p isoform was found to be associated with the transcription factor DYRK1B, and is involved in acquired resistance to dabrafenib in melanoma cells by regulating ADAM9 and VEGF-A." (PMID 39594467, 2024). "Dual-specificity tyrosine phosphorylation-regulated kinase 1B-DYRK1B is activated by the RAF-MEK1/2-ERK1/2 signalling pathway in melanoma and would be related to the promotion of cell differentiation." (PMID 39594467, 2024). "In addition, overexpression of Dyrk1B has been reported in breast, ovarian, and cervical cancer and in melanoma." (PMID 38675189, 2024). "Finally, similar results were obtained in the A375 melanoma cell line (BRAFV600E), where selumetinib caused a dose-dependent inhibition of ERK1/2 signalling and an increase in expression of DYRK1B as well as BIMEL, which is known to be repressed by the ERK1/2 pathway." (PMID 26346493, 2016). "Indeed, when we treated the melanoma cell line MelJuso (HRASG13D/NRASQ61L) with 1 μM selumetinib this strongly and immediately inhibited ERK1/2 signalling and increased the expression of DYRK1B after a delay of 8 h." (PMID 26346493, 2016).
cardiac hypertrophy (3 papers, 2023 to 2025). "In contrast, DYRK1B knockout mice were cardioprotected from afterload-induced cardiac hypertrophy and contractile dysfunction." (PMID 40002350, 2025).
cervical cancer (3 papers, 2015 to 2024). A primary or metastatic malignant neoplasm involving the cervix. "Studies on cervical cancer revealed that the expression of DYRK1B protein increases in parallel with the progression of cervical lesions, showing a high expression in cervical cancer tissues and cells." (PMID 38139175, 2023). "The expression of Dyrk1B in the cervix, including cervical cancer, awaits exploration." (PMID 26307683, 2015).
liposarcoma (3 papers, 2018 to 2024). A usually painless malignant tumor that arises from adipose tissue. "We then examined the association between the level of DYRK1B expression and the prognostic significance of pathology subtype in liposarcomas." (PMID 29568347, 2018). "High expression of DYRK1B was associated with a worse prognosis for patients with liposarcoma." (PMID 33500384, 2021). "High expression of DYRK1B is associated with poor outcomes, which may serve as a prognostic and predictive biomarker in liposarcoma patients." (PMID 29568347, 2018). "To characterize the functional role of DYRK1B in liposarcoma, we investigated the inhibition effect of DYRK1B in liposarcoma by small molecule kinase inhibitor AZ191 and RNAi." (PMID 29568347, 2018). "We then investigated the potential mechanism of inhibition of DYRK1B on the growth of liposarcoma cells." (PMID 29568347, 2018). "We next investigated the effect of DYRK1B inhibition on the abilities of liposarcoma cell migration and invasion." (PMID 29568347, 2018). "To further confirm the effect of DYRK1B knockdown on liposarcoma cells, we also applied DYRK1B targeted endoribonuclease-prepared siRNA (esiRNA) in liposarcoma cell lines." (PMID 29568347, 2018). "To further confirm the effects of inhibition DYRK1B in liposarcoma, we compared transfection with DYRK1B siRNA to SW872 and SW982 liposarcoma cell lines." (PMID 29568347, 2018). "Our findings demonstrated the DYRK1B protein is overexpressed in the majority of liposarcoma patient specimens as compared with lipoma tissues by IHC analysis." (PMID 29568347, 2018). "To explore the relationship between DYRK1B expression and clinical prognosis, we evaluated DYRK1B staining in liposarcoma patient specimens." (PMID 29568347, 2018). "RNA interference-mediated knockdown of DYRK1B or targeting DYRK1B with the kinase inhibitor AZ191 inhibited liposarcoma cell growth, decreased cell motility, and induced apoptosis." (PMID 29568347, 2018). "To determine the effect of DYRK1B knockdown on liposarcoma cell growth in vitro, we transfected synthetic DYRK1B siRNA into SW872 and SW982 cell lines." (PMID 29568347, 2018). "The results demonstrated that the level of DYRK1B expression were higher in patients with liposarcoma than lipoma patients." (PMID 29568347, 2018). "We also demonstrated that higher expression of DYRK1B is correlated with worse prognosis in liposarcoma." (PMID 29568347, 2018). "Higher Dyrk1B expression levels in liposarcoma are correlated with a poor prognosis." (PMID 38675189, 2024). "In particular, Dyrk1B is highly expressed in colorectal, prostate, and lung cancer; pancreatic ductal adenocarcinomas; rhabdomyosarcomas; osteosarcomas; and liposarcomas." (PMID 38675189, 2024). "Targeting DYRK1B with its inhibitor AZ191 reduced liposarcoma cell growth and motility." (PMID 33500384, 2021). "In addition, the results also showed that the DYRK1B protein was predominantly localized in the cytoplasm of liposarcoma cells." (PMID 29568347, 2018). "To assess whether the observed growth inhibitory effect induced by DYRK1B inhibition on liposarcoma cells was due to an induction of apoptosis, we performed flow cytometric analysis and Western blot assays." (PMID 29568347, 2018). "We then investigated the function roles of DYRK1B in liposarcoma cells." (PMID 29568347, 2018). "In this study, we investigated the functional and therapeutic relevance of DYRK1B in liposarcoma." (PMID 29568347, 2018). "We further evaluated the function of DYRK1B in the proliferation and motility of liposarcoma cells." (PMID 29568347, 2018). "Therefore, in the present study, we performed an immunohistochemistry (IHC) assay to examine the expression of DYRK1B in a microarray of liposarcoma patient tissues." (PMID 29568347, 2018). "In summary, our study revealed that DYRK1B is overexpressed in liposarcoma." (PMID 29568347, 2018). "Future in vivo studies and molecular mechanisms of DYRK1B in liposarcoma should be explored." (PMID 29568347, 2018).
liposarcoma (continued). "Similar results were obtained in DYRK1B siRNA transfected liposarcoma cell lines." (PMID 29568347, 2018). "In the present study, we demonstrated for the first time the crucial role of DYRK1B in liposarcoma." (PMID 29568347, 2018). "Inhibition of DYRK1B resulted in significantly decreased cell growth and motility in liposarcoma." (PMID 29568347, 2018). "Targeting DYRK1B provides a new rationale for treatment of liposarcoma." (PMID 29568347, 2018). "Moreover, the roles of DYRK1B in liposarcoma and the significance of targeting DYRK1B signaling as a putative therapeutic remain unknown." (PMID 29568347, 2018). "Dyrk1B silencing by RNA interference or Dyrk1B inhibition by AZ191 inhibitor suppressed tumor growth, decreased cell motility and migration, and induced apoptosis in the liposarcoma cell lines SW872 and SW982." (PMID 38675189, 2024). "Kaplan-Meier survival analysis showed that the prognosis for liposarcoma patients with high DYRK1B staining was significantly worse than those with negative/low DYRK1B staining group." (PMID 29568347, 2018). "After incubation with DYRK1B siRNA or non-specific siRNA at concentrations ranging from 10 to 80 nM for five days, the MTT assay showed that siRNA-mediated knockdown of DYRK1B significantly reduced liposarcoma cell viability in both cell lines in a dose-dependent manner." (PMID 29568347, 2018).
allergic contact dermatitis (2 papers, 2023 to 2025). An inflammatory skin condition caused by an immune response to direct contact between the skin and an allergen. "Recently, inhibition of DYRK1B was reported to reduce inflammation in an allergic contact dermatitis model by using AZ-DYRK1B-33." (PMID 39985685, 2025).
breast carcinoma (2 papers, 2021). "DYRK1B gene expression was substantially higher in tumor tissues compared with that in normal tissues of all breast cancer patients (p < 0.001)." (PMID 34830933, 2021). "Among all breast cancer patients, DYRK1B expression in TNBC patients (negative expression of ER, PR, and HER2) was relative lower than that in the other subtypes." (PMID 34830933, 2021).
colon adenocarcinoma (2 papers, 2022 to 2023). "Elevated levels of DYRK1B protein and mRNA in tissues of colon adenocarcinoma are essential for tumor initiation and progression, which emphasizes the importance of DYRK1B detection for prognosis purposes." (PMID 38139175, 2023). "DYRK1B was found to have an anti-apoptotic effect in colon adenocarcinoma (COAD) and in global cancer predicted pathways." (PMID 35454940, 2022).
colorectal cancer (2 papers, 2022 to 2024). A primary or metastatic malignant neoplasm that affects the colon or rectum. "Hence, the combined treatment of Dyrk1B inhibition and radiotherapy is a promising therapeutic strategy against colorectal cancer." (PMID 38675189, 2024). "Another DYRK1B interactor is LZTS2, a negative regulator of beta catenin, suggesting its involvement in colorectal cancer." (PMID 35454940, 2022). "In a novel approach aimed at overcoming radiotherapy-related treatment resistance by targeting Dyrk1B kinase activity, the specific Dyrk1B inhibitor AZ191 was used with ionizing radiation (IR) to enhance tumor cell killing under stress conditions in SW620 colorectal cancer cells." (PMID 38675189, 2024).
Down syndrome (2 papers, 2024). "The DYRK1A gene, which is considerably better characterized compared to DYRK1B, is significantly associated with the Down syndrome phenotype." (PMID 38932210, 2024).
glioma (2 papers, 2021 to 2025). A benign or malignant brain and spinal cord tumor that arises from glial cells (astrocytes, oligodendrocytes, ependymal cells). "Another study found that DYRK1A and DYRK1B kinases phosphorylate ID2 on threonine 27 (Thr27), leading to HIF2α destabilization, loss of glioma stemness and inhibition of tumour growth." (PMID 34109727, 2021). "According to their findings in U87 glioma cells, hydroxylation of P332 by PHD1 (prolyl hydroxylase domain protein 1, encoded by the EGLN2 gene) precedes and is required for successful autophosphorylation of Y273 in DYRK1B." (PMID 41444824, 2025). "However, contrary to their observations in U87 glioma cells—where the P333A mutant resembled wild-type DYRK1B—we found that P333A also failed to translocate to the nucleus and was indistinguishable from the P332A mutant." (PMID 41444824, 2025).
hepatocellular carcinoma (2 papers, 2017 to 2024). A malignant tumor that arises from hepatocytes. "Combined treatment with cisplatin and the Dyrk1B inhibitor AZ191 effectively inhibited tumor growth in xenograft tumor assays in BALB/c nude mice injected with Hep3B or PLC8024 hepatocellular carcinoma cell lines." (PMID 38675189, 2024). "Overexpression of DYRK1B-H90P or DYRK1B-R102C in HepG2 hepatoma cells resulted in a higher induction of the key gluconeogenic enzyme, glucose-6-phosphatase (G6Pase), than overexpression of wild type DYRK1B." (PMID 28743892, 2017).
Hyperglycemia (2 papers, 2023 to 2025). An increased concentration of glucose in the blood. "Pharmacological inhibition of DYRK1B abrogated hyperglycemia in diabetic mice, providing a new therapeutic target for treating T2DM." (PMID 40287828, 2025). "We further examined if DYRK1B is responsible for the hyperglycemia in db/db mice." (PMID 40287828, 2025). "Liver-specific Dyrk1b conditional knockout mice were protected from diet-induced hyperglycemia." (PMID 40287828, 2025).
medulloblastoma (2 papers, 2016 to 2020). A malignant, invasive embryonal neoplasm arising from the cerebellum. "DYRK1B was demonstrated to work as a positive regulator in humane medulloblastoma cells (DAOY), as siRNA-mediated KD of DYRK1B eliminated SAG-induced GLI1 induction." (PMID 33081032, 2020). "Harmine treatment of murine BCC cells reduced Gli1 expression in a concentration-dependent manner, and like in human medulloblastoma cells, RNAi mediated perturbation of Dyrk1b efficiently inhibited Gli1 protein expression, while depletion of Dyrk1a did not." (PMID 26784250, 2016). "Importantly and in line with our DYRK1B RNAi data, DYRKi treatment of SAG-treated SUFU-positive (WT MB +SAG) and untreated SUFU-depleted (ΔSufu MB) human medulloblastoma cells prevented GLI1 mRNA expression at comparable IC50 concentrations of 1.16 μM and 1.04 μM, respectively." (PMID 26784250, 2016).
neuroblastoma (2 papers, 2013 to 2024). Neuroblastoma (NB) is the most common solid, extracranial childhood tumor. "We have shown that Dyrk1B promotes cell cycle exit and neuronal differentiation in mouse neuroblastoma cells via cyclin D1 cytoplasmic relocation and proteasomal degradation." (PMID 38294527, 2024). "To elucidate a potential mechanism involving BM88/Cend1, RanBPM and Dyrk1B in cell cycle progression/exit, we transiently co-expressed these proteins in mouse neuroblastoma Neuro 2a cells." (PMID 24312406, 2013). "Further, by co-expression experiments in transiently transfected mouse neuroblastoma Neuro 2a cells, we found that the Cend1-dependent or Dyrk1B-dependent down-regulation of cyclin D1 is reversed following their interaction with RanBPM." (PMID 24312406, 2013). "Specifically, we have demonstrated that Dyrk1B overexpression in mouse neuroblastoma cells promotes cell cycle exit and neuronal differentiation by phosphorylating cyclin D1, followed by its cytoplasmic relocation and subsequent degradation by the 26S proteasome." (PMID 38294527, 2024). "Since Dyrk1B has been previously shown to act as a G0-checkpoint kinase that promotes cell cycle exit and terminal differentiation of proliferating myoblasts, immature male germ cells, and mouse neuroblastoma cells, we investigated the effect of mDyrk1B overexpression on the cell cycle." (PMID 38294527, 2024).
endometrial carcinoma (1 paper, 2020). A malignant tumor arising from the epithelium that lines the cavity of the uterine body. "Additional study showed that DYRK1B was mutated in 4.3% of endometrial carcinoma (UCEC) samples, with significantly worse overall survival for patients harboring the mutated kinase (p < 0.05)." (PMID 33205077, 2020).
endothelial dysfunction (1 paper, 2025). In vascular diseases, endothelial dysfunction is a systemic pathological state of the endothelium (the inner lining of blood vessels) and can be broadly defined as an imbalance between vasodilating and vasoconstricting substances produced by (or acting on) the endothelium. "Previous studies have shown that DYRK1B inhibition can ameliorate endothelial dysfunction and chronic inflammatory diseases." (PMID 40799825, 2025).
fibrosarcoma (1 paper, 2014). A malignant mesenchymal fibroblastic neoplasm affecting the soft tissue and bone. "In conclusion, Rac1 activation attenuates mitogenic signalling through DYRK1B and p27 Ser10 phosphorylation, whereas it stimulates migration in 10nM-stimulated fibroblasts and fibrosarcoma cells." (PMID 25476896, 2014).
Glucose intolerance (1 paper, 2025). Glucose intolerance (GI) can be defined as dysglycemia that comprises both prediabetes and diabetes. "Through both in vivo and in vitro experiments, we demonstrate that DYRK1B promotes hepatic gluconeogenesis and glucose intolerance." (PMID 40287828, 2025).
hyperlipidemia (1 paper, 2022). "In conclusion, loss of mTORC2 rescues steatosis and hyperlipidemia in Dyrk1bAAV-WT mice, indicating that Dyrk1b regulates DNL via mTORC2 activation." (PMID 34855620, 2022). "Increasing Dyrk1b levels in the mouse liver enhanced de novo lipogenesis (DNL), fatty acid uptake, and triacylglycerol secretion and caused NASH and hyperlipidemia." (PMID 34855620, 2022). "Altogether, these data indicate that Dyrk1b causes steatosis and hyperlipidemia in mice independent of its kinase activity." (PMID 34855620, 2022). "Taken together, these data indicate that Dyrk1b stimulates hepatic DNL, which in turn increases TAG secretion, leading to steatosis and hyperlipidemia." (PMID 34855620, 2022).
insulinoma (1 paper, 2017). "Finally, we studied the effect of HSP90 inhibition on endogenous DYRK1B in the RINm5F insulinoma cell line." (PMID 28743892, 2017).
ischemic cardiomyopathy (1 paper, 2025). Ischemic cardiomyopathy is a cardiomyopathy in which a weakness in the muscle of the heart due to inadequate oxygen delivery to the myocardium with coronary artery disease being the most common cause. "Plus, the authors reanalyzed previously published RNA-sequencing datasets and found that DYRK1B upregulated in the ventricular myocardium of hypertrophic, dilative, and ischemic cardiomyopathy." (PMID 40002350, 2025).
leukaemia (1 paper, 2020). "Analysing the expression of potent kinase off-targets of PARP inhibitors in haematological cancers using canSAR53 reveals that DYRK1A and DYRK1B are overexpressed at the mRNA level in several types of leukaemia and lymphoma." (PMID 32066817, 2020).
lung adenocarcinoma (1 paper, 2024). A carcinoma that arises from the lung and is characterized by the presence of malignant glandular epithelial cells. "In the present study, we established A549 lung adenocarcinoma cells with inducible overexpression of DYRK1B to explore the consequences of increased DYRK1B levels beyond cell cycle exit." (PMID 39482615, 2024). "To elucidate the role of DYRK1B in cancer cells, we established a A549 lung adenocarcinoma cell model featuring conditional overexpression of DYRK1B." (PMID 39482615, 2024). "Increased expression of DYRK1B induces mesenchymal traits in A549 lung adenocarcinoma cells." (PMID 39482615, 2024).
nonalcoholic steatohepatitis (1 paper, 2022). "Our investigations showed that DYRK1B levels are increased in the liver of patients with nonalcoholic steatohepatitis (NASH) and in mice fed with a high-fat, high-sucrose diet." (PMID 34855620, 2022).
osteosarcoma (1 paper, 2013). A usually aggressive malignant bone-forming mesenchymal neoplasm, predominantly affecting adolescents and young adults. "Furthermore, the study in osteosarcoma demonstrates that the overall survival rate of patients is negatively correlated with the levels of Mirk/Dyrk1B protein expression." (PMID 23311607, 2013).
psoriasis (1 paper, 2025). An autoimmune condition characterized by red, well-delineated plaques with silvery scales that are usually on the extensor surfaces and scalp. "This supports our finding that C81-mediated DYRK1B inhibition in an imiquimod-induced psoriasis model results in reduced inflammation and induced resolution." (PMID 39985685, 2025).
renal carcinoma (1 paper, 2024). A carcinoma arising from the epithelium of the renal parenchyma or the renal pelvis. "On the other hand, in renal cancer, CLK2 strongly correlated with poor prognosis (p = 3 × 10−8), whereas DYRK1B was indicative of prolonged survival (p = 9 × 10−4)." (PMID 38398225, 2024).
rhabdomyosarcoma (1 paper, 2021). A rare aggressive malignant mesenchymal neoplasm arising from skeletal muscle. "Because DYRK1B (i) is important for rhabdomyosarcoma growth, (ii) can block HH signaling, and (iii) is a novel ERK2 substrate, it is possible that ERK represses the HH pathway via DYRK1B." (PMID 34172934, 2021).
serous ovarian cancer (1 paper, 2026). "This study aims to explore the synergistic effect and molecular mechanism of the bispecific tyrosine phosphorylation-regulated kinase 1B (DYRK1B) inhibitor AZ191 combined with the PARP inhibitor Niraparib on high-grade serous ovarian cancer (HGSOC)." (PMID 42072479, 2026).
sleep-disordered breathing (1 paper, 2025). "We found that DYRK1B was highly upregulated in patients with impaired cardiac contractility or sleep-disordered breathing." (PMID 40002350, 2025). "In this large representative study cohort with cardiovascular high-risk patients, we found that an impaired cardiac function as well as sleep-disordered breathing (SDB), including various oxidative stress parameters, were associated with an increased myocardial DYRK1B expression." (PMID 40002350, 2025).